PTCH1 (patched 1)
Description:
Negative regulator of the smoothened signaling pathway, which acts as a receptor for hedgehog (SHH, IHH and DHH) morphogens. In absence of hedgehog, acts as an inhibitor of smoothened protein (SMO) by preventing SMO access to cholesterol: mechanistically, acts as a cholesterol transporter, which depeletes cholesterol from the outer leaflet of plasma membrane, thereby preventing cholesterol-binding to the extracellular CRD region of SMO. Hedgehog-binding inhibits PTCH1 cholesterol transporter activity, promoting SMO activation by cholesterol and transduction of the smoothened signaling pathway. Molecular mechanism governing cholesterol transport are still unclear: may move cholesterol from the outer to the inner leaflet of the membrane in exchange for potassium or sodium ion export in the opposite direction. Seems to have a tumor suppressor function, as inactivation of this protein is probably a necessary, if not sufficient step for tumorigenesis.
Synonyms: PTC; PTC1; PTCH; BCNS; SLC65B1; BCNS1; NBCCS
Tractability: Small molecule: a structure with a bound ligand is known. Antibody: its Gene Ontology location is reachable by antibodies, with high confidence; UniProt places it where antibodies can reach, with medium confidence; UniProt predicts a signal peptide or a membrane-spanning region. PROTAC: UniProt records ubiquitination sites on it; ubiquitination databases record sites on it.
Gene: Protein-coding gene on chromosome 9 (95,442,980 to 95,517,057, reverse strand). Ensembl gene ENSG00000185920.
Subcellular location: Cell membrane; Cell projection, cilium membrane
Subcellular location (Human Protein Atlas): Golgi apparatus; Primary cilium
Pathways (Reactome):
Signal Transduction: Activation of SMO; Class B/2 (Secretin family receptors); GLI proteins bind promoters of Hh responsive genes to promote transcription; Hedgehog 'off' state; Hedgehog 'on' state; Ligand-receptor interactions
Gene Ontology:
Molecular function: cholesterol binding; cyclin binding; hedgehog family protein binding; hedgehog receptor activity; intramembrane lipid transporter activity; protein binding; smoothened binding; heparin binding; patched binding; protein-containing complex binding
Biological process: cellular response to cholesterol; limb morphogenesis; metanephric collecting duct development; negative regulation of osteoblast differentiation; negative regulation of smoothened signaling pathway; negative regulation of transcription by RNA polymerase II; neural tube patterning; pharyngeal system development; positive regulation of cholesterol efflux; protein localization to plasma membrane; smooth muscle tissue development; somite development; animal organ morphogenesis; brain development; dorsal/ventral pattern formation; embryonic limb morphogenesis; negative regulation of multicellular organism growth; neural plate axis specification; protein processing; regulation of smoothened signaling pathway; commissural neuron axon guidance; lipid translocation; liver regeneration; negative regulation of cell division; negative regulation of DNA-templated transcription; and 11 more
Cellular component: apical part of cell; caveola; Golgi apparatus; perinuclear region of cytoplasm; plasma membrane; ciliary membrane; endocytic vesicle membrane; non-motile cilium membrane; axonal growth cone; cilium; dendritic growth cone; membrane; midbody; postsynaptic membrane
Genetic constraint (gnomAD): Loss-of-function variants: 14 observed, 149.63 expected, observed/expected ratio (o/e) 0.0936, 90% interval 0.061 to 0.15. The upper end of that interval is the gene's LOEUF score, 0.15, which puts it in group 1 of 6, group 1 being the genes least tolerant of losing a copy. Missense variants: 1,623 observed, 2,009.6 expected, observed/expected ratio (o/e) 0.81, 90% interval 0.77 to 0.84. Synonymous variants: 833 observed, 822.61 expected, observed/expected ratio (o/e) 1.01, 90% interval 0.96 to 1.07.
Gene-disease validity (ClinGen):
ClinGen rates the evidence that PTCH1 causes each of these diseases.
nevoid basal cell carcinoma syndrome (autosomal dominant): Definitive. A rare hereditary disorder due to autosomal dominant transmission with hamartosis characterized by multiple early-onset basal cell carcinoma (BCC), multiple jaw keratocysts and skeletal abnormalities.
Cancer hallmarks: suppression of growth (promotes); change of cellular energetics
Homologues: Orthologues: macaque PTCH1 (99% identical), chimpanzee PTCH1 (98% identical), pig PTCH1 (96% identical), dog PTCH1 (96% identical), mouse Ptch1 (96% identical), rat Ptch1 (95% identical), guinea pig PTCH1 (92% identical), rabbit PTCH1 (87% identical), tropical clawed frog ptch1 (81% identical), zebrafish ptch1 (75% identical), Drosophila melanogaster ptc (34% identical), Caenorhabditis elegans ptc-1 (31% identical), and 4 more. Paralogues in human: PTCH2 (46% identical), NPC1L1 (18% identical), NPC1 (18% identical), PTCHD3 (13% identical), DISP1 (12% identical), DISP2 (12% identical), PTCHD1 (12% identical), DISP3 (11% identical), PTCHD4 (11% identical), SCAP (9% identical).
Diseases named in the same sentence as PTCH1 in open-access papers:
PTCH1 is named in the same sentence as 255 diseases in open-access papers, as found by Europe PMC text mining. Sharing a sentence is not in itself a finding about the gene and the disease. The quoted sentences say what the papers report.
Gorlin syndrome (203 papers, 2006 to 2026). "The clinical features of these individuals are described and compared with 11 additional mosaic probands with confirmed PTCH1 variants and/or clinically diagnosed Gorlin syndrome identified from the literature." (PMID 41888819, 2026). "This case highlights the value of transcript-level functional assays for interpreting PTCH1 splice-site variants and supports individualized, toxicity-guided sonidegib scheduling in selected patients with Gorlin-Goltz syndrome." (PMID 41816662, 2026). "BACKGROUND: Individuals meeting clinical diagnostic criteria for Gorlin syndrome typically harbor germline pathogenic variants in PTCH1 or SUFU." (PMID 41888819, 2026). "The most well-known is Gorlin syndrome, also known as nevoid basal cell carcinoma syndrome, an autosomal dominant disorder caused by pathogenic variants in the PTCH1 gene on chromosome 9q22.3." (PMID 41477401, 2025). "Researchers have discovered that patents with Gorlin-Goltz syndrome have mutations in the PTCH1 gene, and the immunohistochemical results suggested that the OKC and POKC lesions were caused by a genetic alteration in the patients’ PTCH1-GLI gene." (PMID 41168833, 2025). "The most common BCC syndrome, Gorlin syndrome or basal cell nevus syndrome, is an autosomal dominant (AD) disorder most frequently associated with PTCH1 mutation, while PTCH2 and SUFU are less commonly implicated." (PMID 40290801, 2025). "Gorlin syndrome, also known as nevoid basal cell carcinoma syndrome, arises from germline mutations in the PTCH1 gene, a key component of the Hedgehog signaling pathway leading to early onset BCC." (PMID 40026985, 2025). "Mouse models recapitulate these findings, with Ptch1 deletion causing elevated bone mass and specific point mutations (e.g., DL variant) producing basal cell nevus syndrome‐like skeletal defects." (PMID 40857061, 2025). "Case 1 is a boy, born at term who was diagnosed with Gorlin syndrome, a condition caused by a pathogen heterozygous variant in the PTCH1 gene." (PMID 39953745, 2025). "Early studies identified germline mutations in PTCH1 that are associated with Gorlin syndrome, an inherited disease predisposing to early onset of BCCs, and they found PTCH1 mutations in sporadic BCCs." (PMID 39201498, 2024). "Remarkably, mice with a single functional copy of the Ptch1 gene (Ptch1+/−) recapitulate most features of Gorlin syndrome, including susceptibility to MB and other tumors development, as well as radiation hypersensitivity." (PMID 39594660, 2024). "Germline mutations in multiple macrocephaly syndrome genes are known to be an increased cancer risk, including PTEN (Cowden syndrome) and PTCH1 (Gorlin syndrome)." (PMID 38703765, 2024). "It is estimated that 60–70% of individuals with classical manifestations of Gorlin syndrome harbor germline pathogenic variants in the PTCH1 gene, with most of these variations leading to a loss of protein function." (PMID 38534460, 2024). "Heterozygous germline mutations in the PTCH1 gene in humans cause Gorlin syndrome, also known as nevoid basal cell carcinoma syndrome." (PMID 39594660, 2024). "Basal cell nevus syndrome (BCNS), commonly known as Gorlin Syndrome, is an autosomal dominant genetic condition caused by a defective allele in the PTCH1 gene located on chromosome 9q." (PMID 38534742, 2024). "It has been suggested that new lesion development in Gorlin syndrome requires the development of additional resistance mutations in PTCH1." (PMID 37887561, 2023). "Following the discovery of a germline mutation in the patched homolog 1 (PTCH1) gene in basal cell nevus syndrome, mutations in genes associated with the HH signaling pathway, including PTCH1 and smoothened homolog (SMO), were discovered in sporadic BCCs." (PMID 35870014, 2023). "Another mutation, responsible for Gorlin syndrome (a tumor-prone condition) and predisposing patients to medulloblastoma, is in the PTCH1 gene, a member of the hedgehog signaling pathway." (PMID 36831595, 2023).
Gorlin syndrome (continued). "Model 1 is not consistent with the requirement of cations for PTCH1 function or with anionic triad mutants that render PTCH1 less functional and are associated with severe co-occurrences of Gorlin’s syndrome." (PMID 37611095, 2023). "Except in Gorlin syndrome, for which PTCH1 variants have been reported, only few gene variants have been described in fibromas: a SMARCA4 variant associated with PTCH1 variant in one case and an IDH1 variant associated with Ollier disease in one case." (PMID 38136408, 2023). "Mice with mutations in PTC, an orthologue of human PTCH1, develop many of the characteristics of Gorlin syndrome and exhibit a high incidence of rhabdomyosarcomas." (PMID 38137885, 2023). "Germline inactivating mutations in PTCH1 were associated with Gorlin Syndrome, a genetic predisposition to multiple basal cell carcinoma and medulloblastoma." (PMID 37628631, 2023). "NESCs derived from iPSCs of patients with Gorlin syndrome bearing PTCH1 mutation displayed neural characteristics and the ability to recapitulate SHH medulloblastoma upon orthotopic engraftment in the murine model." (PMID 36831595, 2023). "Gorlin–Goltz syndrome, also known as nevoid basal cell carcinoma syndrome, is an autosomal dominant disease characterized by multisystemic developmental defects caused bypathogenic variants such as patched-1(PTCH1) gene variants and/or SUFU gene variants." (PMID 37564720, 2023). "The main syndromic predisposition to medulloblastoma is Gorlin syndrome which is characterised by multiple skin basal cell carcinoma, macrocephaly and jaw cysts with two proven gene associations (PTCH1 and SUFU) accounting for ~ 70% of cases." (PMID 36961676, 2023). "Gorlin-Goltz syndrome is caused by mutations in the protein patched homolog 1 (PTCH1) gene that codes for a transmembrane receptor, which recognizes the sonic hedgehog (SHH) signaling protein." (PMID 35843976, 2022). "In Gorlin syndrome, which shows basal cell carcinoma predisposition, identification of the patched 1 gene (PTCH1) mutation was a dramatic breakthrough in understanding the carcinogenesis of basal cell carcinoma." (PMID 36233269, 2022). "Owing to the concomitant presence of a mandibular bone cyst, genetic testing was performed, and a PTCH1 gene mutation was confirmed, leading to the diagnosis of Gorlin syndrome." (PMID 36686750, 2022). "Patients with SUFU mutations have a 20-fold higher risk of developing medulloblastoma (33%) than patients with PTCH1 mutations in Gorlin syndrome (<2%)." (PMID 35843976, 2022). "Gorlin syndrome is caused by a mutation in PTCH1, a tumor suppressor gene located on chromosome 9q22.32." (PMID 35843976, 2022). "Inherited PTCH1 loss-of-function mutations result in Gorlin syndrome (a.k.a. basal cell nevus syndrome), an autosomal dominant familial cancer syndrome characterized by basal cell carcinomas among other abnormalities." (PMID 35798968, 2022). "Patients with basal cell nevus syndrome, also known as Gorlin syndrome, have a rare heritable inactivation of PTCH1, predisposing them to BCCs with relatively few background mutations." (PMID 36473848, 2022). "Mutations in these residues impair the ability of PTCH1 to block Hh signaling and have been linked to a familial cancer predisposition syndrome called Gorlin’s syndrome." (PMID 34698632, 2021). "Gorlin syndrome is an autosomal dominant neurocutaneous disease mainly triggered by PTCH1 gene mutations." (PMID 33494284, 2021). "The most frequent mutations attributed to causing Gorlin syndrome are germline loss of function mutations affecting PTCH1 on chromosome 9q22.3." (PMID 34359772, 2021). "We previously reported the presence of mutations in PTCH2 and BOC, alongside PTCH1, in four unrelated patients with Gorlin syndrome patient via exome sequencing." (PMID 34674729, 2021).
Gorlin syndrome (continued). "In Gorlin syndrome, germline inactivation of one copy of the PTCH1 gene followed by somatic loss of the second allele result in loss of SMO suppression and hence constitutive overexpression of the HH signal." (PMID 34359772, 2021). "Basal Cell Nevus Syndrome (BCNS) is an autosomal dominant inherited disease caused by PTCH1 (9q22.3‐q31) germline mutations." (PMID 34021633, 2021). "Previously, we observed via exome sequence analysis that two out of four patients with Gorlin syndrome exhibited mutations in both the PTCH1 and PTCH2 genes." (PMID 34674729, 2021). "This study aimed to identify common gene mutations other than PTCH1 in simultaneously occurring basal cell carcinomas in patients with Gorlin syndrome via exome sequencing analysis." (PMID 34674729, 2021). "According to recent studies, PTCH1 mutation is the cause of basal cell nevus syndrome (also known as Gorlin syndrome), which significantly increases the risk of patients with BCC and MB." (PMID 33653381, 2021). "Gorlin syndrome, due to pathogenic mutations in PTCH1 and SUFU genes, is associated with increased risk of developing BCC." (PMID 33509032, 2021). "Gorlin syndrome (GS), also known as nevoid basal cell carcinoma syndrome, is a neurocutaneous disorder linked to heterozygous mutations in PTCH1 (60–85%) and SUFU (<10%), two important genes of the Sonic Hedgehog signaling pathway." (PMID 35096710, 2021). "Heterozygous LOF mutations in PTCH1 cause basal cell nevus syndrome (BCNS), also known as Gorlin syndrome." (PMID 34884862, 2021). "Heterozygous variants in PTCH1 are associated with BCNS (also known as Gorlin-Goltz syndrome) and holoprosencephaly (HPE), where ocular developmental abnormalities, including C/M, are classified as minor diagnostic criteria." (PMID 33418956, 2021). "Majority of Gorlin syndrome cases are caused by mutations in PTCH1 (Patched1) gene, which is part of the Hedgehog (Hh) molecular pathway." (PMID 32964316, 2020). "Despite comparable proliferative activity, Gln-iPSCs consistently developed medulloblastoma, i.e. Gorlin syndrome-associated tumor, with secondary somatic mutations of the PTCH1 gene." (PMID 32436863, 2020). "Mutations in the PTCH1 gene are associated with Gorlin syndrome, an autosomal dominant disorder characterized by the occurrence of multiple BCCs, but are also the most frequent mutations observed in sporadic BCCs." (PMID 32961989, 2020). "The mouse phenotype was partly recapitulated in patients with Gorlin syndrome caused by inactivating mutations of one of the PTCH1 alleles." (PMID 32933018, 2020). "Patients afflicted by Gorlin syndrome present with loss of PTCH1 heterozygosity, increasing the likelihood of developing a distinct set of solid tumors: BCC, medulloblastoma, and rhabdomyosarcoma." (PMID 32957513, 2020). "In literature, many cases of PTCH1 mutations are described, and they have always been related to Gorlin syndrome." (PMID 31578813, 2020). "In this study, we generated iPSCs derived from fibroblasts of four patients with Gorlin syndrome (Gln-iPSCs) with heterozygous mutations of the PTCH1 gene." (PMID 32436863, 2020). "The first link between BCC and the Hh pathway was revealed in the context of the discovery of loss-of-function mutations in PTCH1 gene in patients with Gorlin syndrome." (PMID 32961989, 2020). "Since the discovery of the PTCH1 gene as being responsible for Gorlin syndrome in 1996, more than 200 sequence mutations have been reported to date including nonsense, missense, and splicing variants, as well as insertions and deletions." (PMID 31979112, 2020).